GFAP (glial fibrillary acidic protein)
Diseases named in the same sentence as GFAP in open-access papers (continued):
Sharing a sentence is not in itself a finding about the gene and the disease.
Alexander disease (continued). "Here we show that the fluid levels of GFAP increase markedly in individuals with Alexander disease, a genetic disorder that results from mutations in GFAP itself, particularly in the CSF." (PMID 26478912, 2015). "Alexander's disease is a neurodegenerative genetic disease that has been shown to be a result of mutations in the GFAP gene." (PMID 25365803, 2014). "Alexander disease (closely related to GAN) is caused by dominantly-acting gain of functional mutations in GFAP." (PMID 24860645, 2014). "Alexander’s disease is a genetic disease caused by gain-of-function point mutations in the GFAP gene." (PMID 25426477, 2014). "Mutations in GFAP are responsible for Alexander’s disease, a rare disorder characterized by severe developmental delay, increased head size, and seizures." (PMID 24410870, 2014). "Alexander disease is a neurodegenerative disease caused by mutations in the glial fibrillary acidic protein (GFAP), leading to aggregates of GFAP and chaperones called Rosenthal fibers." (PMID 24256636, 2013). "Alexander disease was diagnosed by gene examination of the mutation of a glial fibrillary acidic protein." (PMID 23890466, 2013). "Alexander disease is a rare disorder resulting from a glial fibrillary acidic protein gene mutation which causes progressive degeneration of white matter." (PMID 23890466, 2013). "Alexander disease is a rare disorder resulting from a glial fibrillary acidic protein (GFAP) gene mutation which causes progressive degeneration in white matter." (PMID 23890466, 2013). "In the LD related to GFAP mutations (Alexander disease), the inability to form proper astrocytic GFAP networks coexists with incomplete maturation of astrocytes and insufficient myelin formation." (PMID 22737209, 2012). "We describe the clinical and cerebral imaging features of a female newborn with neonatal-onset Alexander disease caused by a heterozygous de novo point mutation c.1106T > C; p.(Leu369Pro) located in the coil 2B area of the glial fibrillary acidic protein (GFAP)." (PMID 41443241, 2025). "Alexander disease (AxD) is a rare leukodystrophy caused by dominant gain-of-function mutations in the gene encoding the astrocyte intermediate filament, glial fibrillary acidic protein (GFAP)." (PMID 38558318, 2024). "Astrocytes may also exhibit cell-autonomous disturbances, which can occur in astrocytopathies resulting from mutated alleles of astrocytic genes (e.g., GFAP in Alexander disease)." (PMID 38991663, 2024). "There are various types of Alexander disease caused by distinct GFAP mutations." (PMID 38920997, 2024). "Although the genetic basis linking GFAP mutations with Alexander disease has been firmly established, the initiating events that promote GFAP accumulation and the role of Rosenthal fibers (RFs) in the disease process remain unknown." (PMID 38782207, 2024). "Genetic mutations affecting the GFAP acidic filament protein cause Alexander disease." (PMID 38920997, 2024). "Interestingly, several pathogenic mutations in this part of the 1A subdomain of the homologous protein glial fibrillary acidic protein (GFAP) cause Alexander disease, which belongs to the leukodystrophies (MIM, #203450)." (PMID 36497166, 2022). "GFAP has been implicated causally in animal models of AD and Alexander’s disease." (PMID 35890250, 2022). "In addition, hiPSC derived astrocytes with GFAP mutations have been shown to suppress human OPC differentiation in an in vitro model of Alexander’s disease." (PMID 35600072, 2022). "Post-translational modifications (PTMs) previously reported for GFAP include site-specific phosphorylations associated with Alexander’s disease, PD, and FTLD; acetylations at six lysine residues in amyotrophic lateral sclerosis (ALS); and citrullination at five arginine residues in AD." (PMID 35890250, 2022). "GFAP mutations result in Rosenthal fibers in Alexander disease." (PMID 36552122, 2022).
Alexander disease (continued). "Mode of inheritance for Alexander disease showed an autosomal dominance pattern with mutation studied in GFAP gene acting as a gain of function mutation leading to disorder in dimerization of intermediate filaments resulting in accumulation of abnormal proteins and cytoskeleton collapse." (PMID 35698668, 2022). "Alexander’s disease, caused by mutations in glial fibrillary acidic protein (GFAP), which forms the cytoskeleton of astrocytes, is a leukoencephalopathy resulting in cerebral white matter lesions due to abnormalities in the vascular endothelium and oligodendrocytes." (PMID 35269435, 2022). "Alexander disease is a leukodystrophy caused by heterozygous mutations of GFAP gene." (PMID 34950187, 2021). "Alexander disease (AxD) represents the first example of an LD caused by a primary astrocyte dysfunction since it is caused by sporadic dominant mutations in the GFAP gene encoding the GFAP protein, the astrocyte-specific marker." (PMID 35008700, 2021). "Alexander disease is caused by mutations in the glial fibrillary acidic protein (GFAP)." (PMID 33381506, 2020). "Alexander disease is intrinsically linked to heterozygous mutations of GFAP gene." (PMID 32630739, 2020). "Additionally, high levels of pathological CHI3L1 release have been observed in Alexander disease, a leukodystrophy which results in a dysregulation of myelination, caused by a glial fibrillary acidic protein (GFAP) mutation in astrocytes." (PMID 31561550, 2019). "We and others quickly found that nearly all Alexander disease patients carried heterozygous missense mutations in the coding region of GFAP, and that such mutations could account for all forms of the disease." (PMID 31838996, 2019). "Since so little is understood about the normal functions of GFAP, it is difficult to discuss in precise terms exactly how Alexander disease-associated mutations might cause gain or loss of any particular functions." (PMID 31838996, 2019). "Interestingly, Alexander’s disease is due to mutations in the GFAP gene that result in decreased solubility and subsequent deposition of the GFAP protein within the cytoplasm of the white matter fibrous astrocytes." (PMID 29922147, 2018). "Additionally, GFAP levels considerably increased in CSF from patients suffering from Alexander disease, a genetic disorder caused by mutations in the GFAP gene, leading to myelin abnormalities in the midbrain and cerebellum." (PMID 30487774, 2018). "Alexander disease is a rare neurodegeneration caused by mutations in a glial gene GFAP." (PMID 29765022, 2018). "Alexander disease is caused by dominant gain-of-function mutations in the astrocyte-specific cytoskeletal intermediate filament protein glial fibrillary acidic protein (GFAP) gene." (PMID 28638987, 2017). "Rosenthal fibers (RFs) are distinctly characteristic features of the astrocyte pathology in Alexander Disease (AxD), a neurodegenerative disorder caused by heterozygous mutations in the gene encoding glial fibrillary acidic protein (GFAP), the major intermediate filament in astrocytes." (PMID 28359321, 2017). "Based on the association of GFAP variations with Alexander disease and due to the atypical and somewhat subtle presentation of neurological sequelae in our patient, additional phenotypic information was collected to improve our phenotype‐to‐genotype association." (PMID 27648269, 2016). "Such a variety of NIID clinical manifestations depending on disease onset ages may resemble Alexander disease that is a white matter disease caused by GFAP (glial fibrillary acidic protein) gene mutation and clinical phenotype is different by onset age." (PMID 27797808, 2016). "Alexander disease is mainly caused by a gene mutation encoding glial fibrillary acidic protein, although the underlying pathomechanism remains unclear." (PMID 27402089, 2016).
Alexander disease (continued). "Many disease‐associated variants have been described in the C‐terminus of GFAP, as well as variants in paralogous proteins at the same or similar positions, highlighting the importance of the tail domain in Alexander disease and in other disease‐associated IF III proteins." (PMID 27648269, 2016). "Alexander disease is a rare, progressive, and generally fatal neurological disorder that results from dominant mutations affecting the coding region of GFAP, the gene encoding glial fibrillary acidic protein, the major intermediate filament protein of astrocytes in the CNS." (PMID 26478912, 2015). "Although there is some evidence that autophagy is spontaneously elevated in Alexander disease, we considered whether the lithium-induced decrease in GFAP might be associated with a further increase in this degradation pathway." (PMID 26378915, 2015). "It is intriguing to speculate therefore that loss of gigaxonin affects GFAP, causing accumulation and aggregation of this protein, in a manner similar to its effects on other IFs, and may even produce Alexander disease–like pathology." (PMID 24860645, 2014). "Alexander disease (AxD) is a rare and severe neurodegenerative disorder caused by mutations in glial fibrillary acidic protein (GFAP)." (PMID 39308436, 2025). "Alexander disease (AxD) is rare leukodystrophy caused by a mutation in the glial fibrillary acidic protein (GFAP) gene." (PMID 40329038, 2025). "Alexander disease (AxD) is a rare neurological disorder caused by dominant gain-of-function mutations in the gene for glial fibrillary acidic protein." (PMID 40064497, 2025). "Alexander disease (AxD) is a leukodystrophy caused by mutations in the astrocytic filament gene GFAP." (PMID 39868835, 2025). "Interestingly, the adult form of Alexander’s disease, which is caused by mutations in the GFAP gene, frequently exhibits cerebellar signs including tremor, and up to 45% of patients with autoimmune GFAP-astrocytopathy have tremor." (PMID 40518460, 2025). "Alexander disease (AxD) is an ultra-rare form of leukodystrophy caused by a dominant mutation in the glial fibrillary acidic protein (GFAP) gene." (PMID 40329038, 2025). "Alexander disease (AxD) is a rare leukodystrophy caused by gain-of-function mutations in the glial fibrillary acidic protein (GFAP) gene, located on chromosome 17q21, which encodes an intermediate filament protein primarily expressed in astrocytes." (PMID 41303265, 2025). "Alexander disease (AxD) is an autosomal dominant leukodystrophy caused by mutations in the gene encoding glial fibrillary acidic protein (GFAP), which is an intermediate filament‐III protein uniquely found in astrocytes in the central nervous system (CNS)." (PMID 39868835, 2025). "Alexander disease (AxD) is a neurodegenerative disease caused by dominant gain-of-function mutations in the gene for GFAP (glial fibrillary acidic protein), an intermediate filament protein expressed by astrocytes in the CNS." (PMID 38236817, 2024). "Alexander disease (AxD) is an autosomal dominant astrocytopathy that presents in patients with monoallelic mutations in the GFAP gene." (PMID 39276676, 2024). "Alexander disease (AxD) is caused by mutations in the gene for glial fibrillary acidic protein (GFAP), an intermediate filament expressed by astrocytes in the central nervous system." (PMID 37048051, 2023). "This new point of view is consistent with recent evidence about Alexander disease (AxD), a severe form of leukodystrophy mainly caused by GFAP mutation." (PMID 37886397, 2023). "In Alexander disease (AxD), a heterozygous mutation in GFAP causes hypertrophy and accumulation of cytoplasmic protein inclusions called Rosenthal fibers within astrocytes." (PMID 35535566, 2022).
Alexander disease (continued). "Experimental models suggest that the pathology of some disorders might even be primarily driven by astrocyte defects, for example in Alexander Disease, which is caused by mutations in the GFAP gene, spinocerebellar ataxia 7 (SCA7), inflammatory cerebellar ataxias, and some forms of epilepsy." (PMID 35546493, 2022). "Furthermore, in a previous collaboration, we detected upregulation of ICOSLG at the transcriptional level in both post-mortem brain samples and hiPSC-derived astrocytes from patients with Alexander Disease, a neurodegenerative disease caused by mutations in GFAP." (PMID 35592112, 2022). "For example, in Alexander disease (AxD), a rare and usually fatal neurodegenerative disorder that is associated with GFAP mutations, plectin in astrocytes accumulates in protein aggregates called Rosenthal fibres (RFs)." (PMID 34572001, 2021). "In addition, HSP27 activates the autophagy-lysosomal pathway in abnormal astrocytes containing Rosenthal fibers in patients of Alexander disease that is an untreatable and fatal neurodegenerative disorder showing seizures caused by heterozygous mutations of GFAP gene." (PMID 32899862, 2020). "Alexander disease (AxD) is a fatal neurodegenerative disorder caused by mutations in glial fibrillary acidic protein (GFAP), which supports the structural integrity of astrocytes." (PMID 31682229, 2019). "The dominant nature of the GFAP variants, coupled with the minimal phenotype associated with complete GFAP deficiency as illustrated in mouse knockouts, supports the hypothesis that Alexander disease is a gain-of-function disease." (PMID 31838996, 2019). "Alexander disease (AxD) is a rare disease caused by mutations in the gene encoding glial fibrillary acidic protein (GFAP)." (PMID 28634469, 2017). "Alexander disease (AxD) is a primary astrocyte disease caused by autosomal dominant mutations in the gene encoding GFAP." (PMID 28700643, 2017). "This is one of the mutations in GFAP that causes Alexander disease (AxD), a fatal neurodegenerative disease characterized by leukodystrophy, macrocephaly, and psychomotor retardation." (PMID 27141937, 2016). "However, the most remarkable evidence of the relevance of GFAP in the physiological roles of astrocytes in maintaining normal brain function is Alexander disease, the devastating leukodystrophy resulting from dominantly acting mutations in the coding region of GFAP." (PMID 25050142, 2014). "AxD (Alexander disease) is a rare disorder caused by heterozygous mutations in GFAP (glial fibrillary acidic protein) resulting in accumulation of the GFAP protein and elevation of Gfap mRNA." (PMID 23432455, 2013). "Alexander's disease is a rare neurodegenerative disorder primarily characterized by upregulation of the GFAP gene and the formation of Rosenthal fibers." (PMID 40448810, 2025). "Mutations in GFAP cause Alexander disease (AxD), a rare and fatal neurological disorder." (PMID 40735838, 2025). "Alexander disease (AxD) is a very rare neurodegenerative disorder caused by a dominant gain-of-function mutation in the glial fibrillary acidic protein (GFAP) gene located in chromosome 17q21, which is pathologically marked by the formation of cytoplasmic aggregates in astrocytes." (PMID 40144630, 2025). "In Alexander disease, GFAP showed degradation products ranging between 25 and 35 kDa in both patients and mouse samples, with a 26 kDa band being the most abundant proteolytic fragment detected in four of the five cases examined." (PMID 38891912, 2024). "Alexander disease (AxD) is a rare genetic disorder, caused by missense mutations in the GFAP (the major intermediate filament protein in astrocytes) gene, resulting in astrocyte dysfunction, accumulation of GFAP aggregates and accumulation of stress protein aggregates (known as RF) in the brain." (PMID 38216970, 2024). "Site‐specific phosphorylation and caspase cleavage of glial fibrillary acidic protein (GFAP) are new biomarkers of Alexander's disease." (PMID 37564024, 2023).
Alexander disease (continued). "Subsequently, HSP-SPAST (SPG4), HSP/ATX-SPG7 (SPG7) as well as ATX-ATXN1 (SCA1), ATX-ATXN2 (SCA2), ATX-ATXN3 (SCA3), ATX-CACNA1A (SCA6), ATX/HSP-SACS (ARSACS), and Alexander’s disease (GFAP) were excluded." (PMID 36768210, 2023). "Alexander's disease (AxD) is a rare autosomal dominant hereditary disorder that is caused by the mutations in the GFAP gene, which encodes the glial fibrillary acidic protein (GFAP)." (PMID 36601294, 2022). "Site-specific phosphorylation (Ser13) has recently been identified to be a better marker of Alexander disease severity than total GFAP alone." (PMID 36012232, 2022). "Astroglial caspase-6 is a key element in Alexander’s disease and known to mediate cleavage of the intermediate filament glial fibrillary acidic protein (GFAP)." (PMID 36347836, 2022). "Recent studies of Alexander disease (AxD) have identified GFAP aggregates and Rosenthal fibers in AxD patient iPSC-derived astrocytes." (PMID 31134525, 2020). "Alexander disease (AD) is a glial fibrillary acidic protein (GFAP) related astrocytopathy characterized by an abundance of Rosenthal fibers in astrocytes, particularly in subpial and subependymal locations." (PMID 32849169, 2020). "Alexander disease (AxD) is a rare neurodegenerative disease of primary astrocyte dysfunction which features gain-of-function mutations in and protein aggregations of the astrocytic protein GFAP." (PMID 31936297, 2020). "For example, mutations in the glial fibrillary acidic protein (GFAP) gene and the eukaryotic translational initiation factor 2B (EIF-2B) gene lead to Alexander’s disease and vanishing white matter disease, respectively." (PMID 31888684, 2019). "But Alexander disease bears little resemblance to the minimal phenotype observed in mouse knockouts of GFAP." (PMID 31838996, 2019). "Alexander disease is characterised pathologically by the presence of Rosenthal fibres, which are long, filamentous eosinophilic fibres largely composed of GFAP protein." (PMID 30467211, 2019). "By introducing Alexander disease (AxD)-associated hotspot mutations (R79C, R239C) into GFAP gene of hPSCs and subsequently inducing astrocyte differentiation, we found that GFAP mutations impaired mitochondrial transfer from astrocytes and reduced astrocytic CD38 expression." (PMID 31327963, 2019). "To probe the direct connection between GFAP and the actin cytoskeleton in Alexander disease, we focused on the spectraplakin proteins, a family of giant cytoskeletal linker proteins, which interact with F-actin and intermediate filaments." (PMID 29765022, 2018). "Here, Wang and colleagues show in animal models of Alexander disease that GFAP mutant brain and cells have greater tissue and cellular stiffness and greater activation of mechanosensitive signaling cascade." (PMID 29765022, 2018). "For example, Alexander disease (MIM, 203450) is caused by mutations in GFAP, encoding glial fibrillary acidic protein." (PMID 29274115, 2018). "A striking neuropathological feature of Alexander disease is the formation of large cytoplasmic aggregates of GFAP, termed Rosenthal fibers." (PMID 29765022, 2018). "Similarly, significant overexpression of human wild-type GFAP in mice causes Rosenthal fiber formation, and models other aspects of Alexander disease as well, raising the possibility that persistently elevated levels of wild-type human GFAP may cause cellular toxicity in some human brain disorders." (PMID 29765022, 2018). "Alexander disease (AxD), first described in 1949 by Alexander, is a rare and fatal CNS disease of genetic origin that is caused by a heterozygous mutation in the glial fibrillary acidic protein (GFAP) gene." (PMID 28634469, 2017). "Alexander disease is a fatal neurological illness characterized by white-matter degeneration and formation of Rosenthal fibers, which contain glial fibrillary acidic protein as astrocytic inclusion." (PMID 27402089, 2016).